LEP (leptin)
Diseases named in the same sentence as LEP in open-access papers (continued):
Sharing a sentence is not in itself a finding about the gene and the disease.
leiomyoma (3 papers, 2023 to 2025). A well-circumscribed benign smooth muscle neoplasm characterized by the presence of spindle cells with cigar-shaped nuclei, interlacing fascicles, and a whorled pattern. "Recent studies have linked the adipocyte coculture or the secretion of leptin from adipose tissue to the promotion of leiomyoma cell proliferation and ECM deposition." (PMID 36771423, 2023). "In our previous publication we have demonstrated that leptin treatment increased pSTAT3/STAT3 signaling in immortalized leiomyoma cells." (PMID 36771423, 2023). "As a result of coculture of leiomyoma cells with adipocytes and leptin treatment, TGF-β3 and VEGF-A expressions are significantly increased." (PMID 36771423, 2023). "In this study, we observe the effect of adipocyte coculture and leptin treatment on human myometrium and leiomyoma cells." (PMID 36771423, 2023). "Leiomyoma cocultured with adipocytes and leptin treatment significantly increased in expression of PCNA and TNF-α." (PMID 36771423, 2023). "Adipocyte coculture and leptin treatment has previously been shown to increase PCNA expression in leiomyoma cells." (PMID 36771423, 2023). "We previously found that leptin promotes human leiomyoma cell proliferation via the JAK/STAT3 and MAPK/ERK pathways." (PMID 37628676, 2023). "The purpose of this study was to investigate the effect of STAT3, ERK, and AKT inhibitors on TGF-β3 and VEGF-A expression in leiomyoma cells cocultured with adipocytes and treated with leptin." (PMID 36771423, 2023). "To further understand the effect of adipocyte on JAK2/STAT3 signaling in leiomyoma development, we cocultured primary and immortalized myometrium and leiomyoma cells with adipocytes and treated the leptin." (PMID 36771423, 2023). "Expression of phosphorylated ERK1/2 (pERK1/2) was significantly higher in immortalized leiomyoma cells cocultured with adipocytes and leptin-treated primary leiomyoma cells." (PMID 36771423, 2023). "Expression of phosphorylated STAT3 (pSTAT3) was significantly higher in immortalized leiomyoma cells cocultured with adipocytes and leptin-treated primary cells." (PMID 36771423, 2023). "We sought to investigate the effect of STAT3, ERK, and AKT inhibitors in PCNA and TNF-α expression in leiomyoma cells cocultured with adipocytes and leptin treatment." (PMID 36771423, 2023). "Our study found that leptin treatment of leiomyoma cells increased pro-inflammatory factors, MCP-1, IFNγ, IL-8, GM-CSF, IL-6, and TNF-a." (PMID 36771423, 2023). "An enzyme-linked immunosorbent assay (ELISA) was used to assess pro-inflammatory, fibrotic, and angiogenic factors in immortalized human myometrium and leiomyoma cells treated with leptin." (PMID 36771423, 2023). "Leptin exerts these effects by stimulating the phosphorylation of STAT-3 in leiomyoma cells." (PMID 40943781, 2025). "Finally, STAT3, ERK, and AKT inhibitor treatment suppressed PCNA, TNF-α, TGF-β3, and VEGF-A intracellular staining intensity in both adipocyte coculture and leptin treated leiomyoma cells." (PMID 36771423, 2023). "The respective inhibitors reduced the levels of pSTAT, pERK1/2, and pAKT and suppressed the intracellular staining intensity of PCNA, TNF-α, TGF-β3, and VEGF-A, in addition to reversing the effect of leptin treatment and adipocyte coculture on leiomyoma cell growth." (PMID 36771423, 2023). "Furthermore, adipocyte coculture and leptin treatment increases leiomyoma cells growth through activation of MAPK/ERK, JAK2/STAT3, and PI3k/AKT signaling pathways." (PMID 36771423, 2023). "Protein expression levels of phosphorylated ERK1/2/total ERK1/2, phosphorylated STAT3/total STAT3, and phosphorylated AKT1/2/3/total AKT1/2/3 were quantified using immunoblotting in immortalized and primary leiomyoma and myometrial cells cocultured with human adipocytes and treated with leptin." (PMID 36771423, 2023).
leiomyoma (continued). "In primary and immortalized leiomyoma cells, expression of phosphorylated AKT (pAKT) was significantly higher in cocultured with adipocytes and leptin-treated immortalized and primary leiomyoma cells." (PMID 36771423, 2023). "Next, we examined the effects of adipocyte coculture or leptin treatment on MAPK/ERK signaling in immortalized and primary leiomyoma and myometrium cells." (PMID 36771423, 2023). "Leptin treatment has previously been shown to augment the effect of STAT3 and ERK inhibitors in leiomyoma cells." (PMID 36771423, 2023). "Leptin induces a tumor-friendly microenvironment through upregulation of pro-inflammatory (IFNγ, IL-8, IL-6, GM-CSF, MCP-1, and TNF-α), fibrotic (TGF-β1, TGF-β2, and TGF-β3), and angiogenic (VEGF-A, HGF, and Follistatin) factors in human leiomyoma cells." (PMID 36771423, 2023). "Furthermore, leptin treatment augmented the effect of STAT3 and ERK inhibitors in human leiomyoma cells." (PMID 36771423, 2023).
leukocytosis (3 papers, 2020 to 2025). "Furthermore, the existence of CE is not predicted by peripheral blood inflammation markers such C-reactive protein (CRP), leukocytosis, leptin, and IL6." (PMID 39941173, 2025).
limb ischemia (3 papers, 2017 to 2022). A ischemia that involves the limb. "Leptin is reportedly expressed by perivascular PDGFRβ+ cells and contributes to transplanted PCs’ proangiogenic activity in a mouse model of limb ischemia." (PMID 35349488, 2022). "Accordingly, the levels of LEP secretion predict the microvascular outcome of APCs transplantation in a mouse limb ischemia model." (PMID 28710369, 2017). "Thus, the assessment of LEP helps to predict the microvascular outcome of APC therapy in a mouse model of limb ischemia." (PMID 28710369, 2017). "Having demonstrated that APC-produced LEP promotes autocrine and angiocrine effects in vitro, we next investigated if the adipokine helps to predict the outcomes of APC therapy in a mouse model of limb ischemia." (PMID 28710369, 2017).
metastasis (3 papers, 2015 to 2021). The spread or migration of cancer cells from one part of the body (where they first appeared) to another. "Taken together, our findings support the importance of the leptin/LEPR/KHDRBS1 axis and of adiponectin in the progression of bone metastasis and suggest their potential application in pharmacological interventions." (PMID 33213024, 2020).
nematode infection (3 papers, 2013 to 2017). "Loss of leptin may consequently enhance Th2 immune responses which are protective during nematode infection." (PMID 23349631, 2013). "Increased chow consumption, weight, and leptin levels have also been detected in mice fed a low-protein diet in previous nematode infection-diet manipulation experiments." (PMID 29358937, 2017). "Leptin expression, however, was not decreased further by N. brasiliensis infection in Cl2MDP-treated mice indicating that the down-regulation of leptin alone in response to nematode infection cannot explain the change in glucose transporters." (PMID 24465430, 2014). "Importantly, leptin enhances Th1, but suppresses Th2 responses; therefore, it is not surprising that the upregulation of Th2 cytokines during nematode infection coincides with reduced leptin expression." (PMID 24465430, 2014). "A reduction in leptin could enhance the protective Th2 immune response to nematode infection." (PMID 23349631, 2013).
nephrotic syndrome (3 papers, 2023 to 2024). A collection of symptoms that include severe edema, proteinuria, and hypoalbuminemia; it is indicative of renal dysfunction. "This study demonstrated the potential of CCL22 and Leptin to predict steroid resistance in the early stages of nephrotic syndrome." (PMID 37744450, 2023). "In addition, urinary leptin levels were markedly higher in a cohort of 30 children with nephrotic syndrome compared to 25 healthy controls, and greatly improved during prednisone therapy." (PMID 37189804, 2023). "Leptin may also play a role in oxidative stress in nephrotic syndrome." (PMID 39139165, 2024). "This study aimed to compare patients with steroid-sensitive nephrotic syndrome (SSNS) and steroid-resistant nephrotic syndrome (SRNS) in terms of CCL22 and Leptin levels." (PMID 37744450, 2023). "The patients were classified based on their response to steroid treatment, and the relationship between serum Leptin and CCL22 levels and steroid sensitivity in children with nephrotic syndrome was analyzed." (PMID 37744450, 2023).
oesophageal cancer (3 papers, 2007 to 2021). "In this study, we have demonstrated for the first time the essential requirement for the small GTPases Ras, Rho and cdc42 in leptin-induced Akt activation in oesophageal cancer cells." (PMID 33582946, 2021). "All these results were consistent and clearly implicate Akt as a downstream mediator in the effects of leptin in oesophageal cancer cells." (PMID 33582946, 2021). "Leptin has also been shown to increase the resistance of oesophageal cancer to chemotherapy in vivo and in vitro." (PMID 33582946, 2021).
oral cancer (3 papers, 2012 to 2017). "Other studies are needed to understand the role of LEPR variants in the development and progression of oral cancers, especially in relation to Leptin levels or in association with the stages of dysplasia." (PMID 26034683, 2014). "Supporting a role of leptin in cancer pathogenesis are reports that DNA polymorphisms in the leptin and ObR genes are associated with increased risk and progression of breast, prostate, and oral cancer." (PMID 22263109, 2012).
Ovarian cyst (3 papers, 2020 to 2026). The presence of one or more cysts of the ovary. "Although metreleptin was approved by the Food and Drug Administration in 2014, it has common side effects like headache, ovarian cysts, ear infection, high levels of protein in the urine, fever, and leptin resistance." (PMID 32164196, 2020). "Regarding LEP, the literature reports that it stimulates, at physiological rates, follicular development and steroidogenesis, but in high quantities, it increases testosterone secretion and promotes the formation of ovarian cysts." (PMID 41532033, 2026).
pancreatic adenocarcinoma (3 papers, 2022 to 2023). "Serum leptin levels may be a good diagnostic and predictive tool for the response to treatment in pancreatic adenocarcinoma patients." (PMID 37444627, 2023).
periapical granuloma (3 papers, 2015 to 2022). Chronic nonsuppurative inflammation of periapical tissue resulting from irritation following pulp disease or endodontic treatment. "Amongst the inflammatory cells present in the periapical granulomas, only macrophages were reactive to leptin antibodies." (PMID 35216099, 2022). "Further studies are required analyzing the expression of LEPR in periapical granulomas in order to fully elucidate the roles of leptin and LEPR in the physiology of periapical chronic inflammatory response." (PMID 25662559, 2015). "The level of leptin mRNA found in periapical granulomas (leptin/cyclophilin ratio: 0.91 ± 0.18) was higher compared to that observed in human pulp samples (leptin/cyclophilin ratio: 0.085 ± 0.015)." (PMID 25662559, 2015). "In conclusion, the expression of leptin in human periapical granulomas demonstrated in the present study, points to a possible role of leptin in periapical immune, inflammatory and reparative responses." (PMID 25662559, 2015). "Analysis of the immunohistochemical expression of anti-leptin antibody showed the presence of leptin+ cells in 13 periapical granulomas (86.6%)." (PMID 25662559, 2015). "The aim of this study was to analyze and characterize the expression of leptin in human periapical granulomas." (PMID 25662559, 2015). "In the present study, the expression of leptin in the inflammatory tissue of periapical granulomas has been demonstrated immunohistochemically." (PMID 25662559, 2015). "After their morphological categorization as periapical granulomas and gradation of the inflammatory infiltrate, they were examined by immunohistochemistry using human leptin policlonal antibodies." (PMID 25662559, 2015). "This study is the first to demonstrate, both immunohistochemically and at the level of mRNA and protein, the expression of leptin in human periapical granuloma samples." (PMID 25662559, 2015). "Since leptin induces endothelial cell proliferation and angiogenesis, the presence of leptin in human periapical granulomas suggest a role of leptin in periapical healing." (PMID 25662559, 2015). "Amongst the inflammatory cells in the periapical granulomas, only macrophages were reactive to leptin antibodies." (PMID 25662559, 2015). "Key words:Apical granuloma, dental pulp, endodontics, leptin, leptin receptor, immune system, immunohistochemistry, periapical inflammatory response." (PMID 25662559, 2015). "For the first time, it has been demonstrated that human periapical granuloma expresses the adipokine leptin." (PMID 25662559, 2015). "The median number of leptin+ cells in periapical granulomas was 1.70 (0.00 -7.4)." (PMID 25662559, 2015). "In the present study, 13 periapical granulomas (86.6%) were reactive to leptin antibodies." (PMID 25662559, 2015). "Leptin+ cells were detected in 13 periapical granulomas (86.6%)." (PMID 25662559, 2015). "The presence of leptin and LEPR mRNAs, determined by a quantitative real-time PCR (qRT-PCR), and leptin and LEPR proteins, analyzed by immunoblot, have also been demonstrated in human periapical granulomas." (PMID 35216099, 2022).
peritonitis (3 papers, 2011 to 2018). Inflammation of the peritoneum (tissue that lines the abdominal wall and covers most of the organs in the abdomen). "In surgically treated patients with peritonitis, an insufficient rise in serum LEP (< 10 ng/mL) is associated with a threefold-increase in the risk of death (sensitivity 94.4, specificity 50%)." (PMID 21943151, 2011). "• These polymorphisms are related with an insufficient increase of LEP serum levels in peritonitis." (PMID 21943151, 2011). "• LEP Gene -2548G > A, and the LEPR Gene 223A > G polymorphisms increase the risk of death in secondary peritonitis with an odds ratio of 4.64 and 3.57, respectively." (PMID 21943151, 2011). "The purpose of this study was to explore the association of genetic polymorphisms of LEP or LEPR with an unfavourable outcome (death) in patients with non-appendicular secondary peritonitis." (PMID 21943151, 2011). "There is also evidence that leptin is produced by intraperitoneal adipocytes, and that increased concentrations of this and other adipokines have a very high sensitivity and specificity for an early diagnosis of peritonitis in patients undergoing peritoneal dialysis." (PMID 25984763, 2015).
pheochromocytoma (3 papers, 2007 to 2023). "Conversely, acute activation of beta-adrenergic receptors has been shown to decrease leptin production by adipocytes in both humans and rodent models, though in a study of pheochromocytoma (PHEO) circulating leptin levels were not suppressed." (PMID 25018768, 2014).
pneumococcal pneumonia (3 papers, 2012 to 2018). A febrile disease caused by STREPTOCOCCUS PNEUMONIAE. "Furthermore, exogenous leptin administration to leptin-deficient mice improved the pulmonary bacterial clearance and survival during pneumococcal pneumonia." (PMID 30618812, 2018). "For example, studies have demonstrated that leptin administration corrects impaired host defense pathways in the setting of mice starved for 48 h prior to induction of pneumococcal pneumonia." (PMID 23145105, 2012).
polyp (3 papers, 2010 to 2020). A usually exophytic mass attached to the underlying tissue by a broad base or a thin stalk. "Of the adipokines associated with polyp number or type, including IP-10, TNF-α and leptin, all are considered pro-inflammatory at elevated concentrations and increase the activity of signaling pathways in their target cells." (PMID 24465801, 2014). "Two adipokines (leptin and IP-10) were the same as for polyp number, and additionally, TNF-α had a statistically significant association with the presence of a tubular adenoma." (PMID 24465801, 2014). "Significant associations were observed between two of these serum adipokines (leptin and IP-10) with polyp number, and a third serum adipokine (TNF-α) showed a trend towards significance (p = 0.09)." (PMID 24465801, 2014).
pregnancy disorder (3 papers, 2020 to 2025). A disorder that is related to pregnancy. "Leptin plays a pro-inflammatory action influencing the pathogenesis of various pregnancy diseases including GDM." (PMID 34652617, 2021). "Although a dysregulation of LEP levels has been found to correlate with the pathogenesis of various pregnancy disorders, including PE, the exact mechanism of action of LEP and its upstream regulation remain unknown." (PMID 32126118, 2020). "A growing number of studies suggest that various adipokines including adiponectin, leptin, visfatin, resistin and tumor necrosis factor α (TNF-α) are dysregulated in GDM and might have pathological significance and a prognostic value in this pregnancy disorder." (PMID 34652617, 2021).
psoriasis vulgaris (3 papers, 2014 to 2020). Plaque psoriasis is the most common presentation of psoriasis. "Leptin gene polymorphism rs2060713 has not been statistically significantly associated with psoriasis vulgaris." (PMID 24600521, 2014).
pulmonary embolism (3 papers, 2022 to 2025). The obstruction of the pulmonary artery or one of its branches by an embolus, sometimes associated with infarction of the lung. "Leptin signaling antagonists also appear to improve outcomes in cardiovascular disease: leptin induces thrombotic events in a mouse model of pulmonary embolism, but event frequency is reduced–and overall survival improved–by treatment with a leptin-neutralizing antibody." (PMID 39439572, 2024).
septic arthritis (3 papers, 2012 to 2018). "Septic arthritis is caused by Staphylococcus aureus; leptin production was found to be downregulated during this infection, in murine model." (PMID 29868503, 2018). "Though exogenous recombinant leptin supply failed in restoring the basal leptin levels and clearance of bacterial load in these animals, it substantially reduced the severity of septic arthritis by regulating the production of inflammatory cytokine IL-6." (PMID 29868503, 2018). "Treatment with leptin in animal models of septic arthritis reduced the severity of joint damage, which may indicate that leptin in the synovial cavity exerts a protective effect against RA-induced joint destruction." (PMID 22584415, 2012).
spondyloarthritis (3 papers, 2017 to 2021). "Interestingly, both serum levels of leptin and resistin were significantly higher as compared with the control group in patients with isolated knee OA and in cases combined with OA with other localization i.e., spondyloarthritis ± hip OA." (PMID 34440223, 2021). "In our previous study involving patients from the German Spondyloarthropathy Inception Cohort (GESPIC) cohort, who had early axial SpA, we found a positive association between visfatin and radiographic spinal progression; leptin and HMW-APN were not investigated." (PMID 28619118, 2017).
synovitis (3 papers, 2014 to 2020). Inflammation of a synovial membrane. "Some studies reported that intraarticular injection of leptin increased synovial hyperplasia in collagen-induced arthritis in mice, and enhanced leptin levels were shown to be associated with synovitis in human OA." (PMID 33361529, 2020). "Finally, the observed synovitis in aged L-PGDS-/- mice may also be due to increased leptin levels." (PMID 33361529, 2020). "IPFP area was neither associated with BMI, body fat, trunk fat, leg muscle strength and patellofemoral synovitis, nor with leptin, IL-6 and TNF-α (data not shown)." (PMID 25008048, 2014).
T-cell lymphoma (3 papers, 2019 to 2026). "Though rare, T-cell lymphoma has been reported in patients with AGL on leptin therapy, and there has been much debate on the association between hyperleptinemia and cancer." (PMID 41700130, 2026).